ARID1A (AT-rich interaction domain 1A)
Diseases named in the same sentence as ARID1A in open-access papers (continued):
Sharing a sentence is not in itself a finding about the gene and the disease.
gastric cancer (continued). "In 2021, Yuan-Hung Lo used primary human gastric organoids combined with gene editing technology to establish the first genetic model of ARID1A mutations, and its multiomics analysis revealed many characteristic phenotypes of ARID1A mutant gastric cancer." (PMID 37537666, 2023). "Loss of ARID1A in gastric cancer is correlated with advanced stage, tumour invasion, lymphovascular invasion, lymph node metastases, and reduced survival, especially in poorly differentiated and early-stage cases." (PMID 38275587, 2023). "Although some studies of gastric cancer suggested that alterations in ARID1A caused better survival, more studies supported that loss of ARID1A was an adverse prognostic factor." (PMID 37366273, 2023). "Mutations in ARID1A are diverse and have been discovered in a variety of malignancies, including gynecological carcinoma, urothelial carcinoma, gastric cancer and lung cancer." (PMID 36869329, 2023). "Many studies have confirmed that ARID1A expression is associated with multiple clinicopathological features of gastric cancer." (PMID 37366273, 2023). "Deficiency of ARID1A is associated with larger tumour size, increased invasion depth, lymph node metastasis and a poor prognosis in gastric carcinomas that are EBV (−) and have preserved MLH1 expression." (PMID 38041544, 2023). "Several previous studies have shown that the loss or mutation of ARID1A tumor suppressor gene promote invasion of several cancers, including neuroblastoma 67, gastric cancer 68, hepatocellular carcinoma 69, and breast cancer." (PMID 35069887, 2022). "Loss of ARID1A is related to size, infiltration depth, lymph node metastasis and poor prognosis of gastric cancer." (PMID 35783357, 2022). "Reportedly, ARID1A-deficient gastric cancer cells are vulnerable to the AKT inhibitor, GSK690693, and the addition of GSK690693 possibly potentiates the suppressive function of conventional chemotherapy." (PMID 36371186, 2022). "In recent years, some scholars have pointed out that the combination of the P13K inhibitor BKM120 with olaparib can inhibit the proliferation of gastric cancer cells with ARID1A deficiency." (PMID 36035159, 2022). "In patients with gastric carcinoma, decreased ARID1A expression was associated with lymph node metastases, tumour infiltration and poor prognosis." (PMID 36420658, 2022). "Epstein–Barr virus (EBV)-associated gastric carcinoma (EBVaGC) is a distinct molecular subtype of gastric cancer characterized by viral infection and cellular abnormalities, including loss of AT-rich interaction domain 1A (ARID1A) expression (lost ARID1A)." (PMID 34469459, 2021). "Recently, decreased mRNA ARID1A and protein expression have been associated with poor prognosis in gastric cancer." (PMID 34414106, 2021). "Inhibition of GCLC leads to apoptotic cell death in ARID1A-deficient cancer cells, and the vulnerability of ARID1A-deficient gastric cancer cells to GSH inhibition is caused by decreased GSH synthesis due to diminished SLC7A11 expression." (PMID 34671561, 2021). "Mutations that disable ARID1A occur in several cancers, including gastric cancer, hepatocyte cancer, breast cancer, and pancreatic cancer, and ARID1A mutations interfere with tumor suppression and cause carcinogenesis through other mechanisms." (PMID 34063990, 2021). "The ARID1A is often mutated in esophageal and gastric cancers and is the canonical cancer gene according to the Cosmic Cancer Gene Census." (PMID 34572812, 2021).
gastric cancer (continued). "A pronounced difference in PD-L1 induction by IFN-γ treatment existed between ARID1A-deficient and control gastric cancer cells." (PMID 35127746, 2021). "Low GSH levels have been shown to increase sensitivity to GSH inhibitors, such as APR‐246, in ARID1A‐deficient ovarian and gastric cancer cell lines." (PMID 34042280, 2021). "This is consistent with reports of colorectal carcinoma, gastric carcinoma, endometrial carcinoma and ovarian endometrioid carcinoma, indicating a correlation between dMMR and loss of ARID1A expression." (PMID 33541386, 2021). "Gastric carcinomas with somatic ARID1A mutations were characterized by a more intense PD-L1 expression than tumors without mutations." (PMID 34572812, 2021). "A study also showed that the lost expression of ARID1A was common in 30% of gastric cancer patients and was associated with poor clinical prognosis." (PMID 32334542, 2020). "Within the gastrointestinal tract, the importance of ARID1a loss in gastric carcinoma and colon carcinoma has been described." (PMID 31906887, 2020). "Loss of ARID1A expression has been found in a broad spectrum of human cancers, including gastric carcinoma (8–29%) and oesophageal adenocarcinoma (9–19%)." (PMID 31906887, 2020). "The association of ARID1A expression with the clinicopathological characteristics of gastric cancer patients was investigated." (PMID 31043675, 2019). "The most commonly mutated gene was ARID1A, which was highly mutated in uterine cancer (14.78%) and stomach cancer (20.92%), as previously reported." (PMID 31504061, 2019). "A meta-analysis including 15 gastric cancer cohorts revealed that low ARID1A expression is associated significantly with worse patient survival and adverse clinicopathological factors, such as lymphatic invasion and lymph node metastasis." (PMID 31043675, 2019). "This cohort of tumours had previously been examined to report ARID1A loss in about 20% of gastric carcinoma, with the loss being prognostically significant." (PMID 31790410, 2019). "ARID1A silencing seems to be inducing a subcellular redistribution of β-catenin from the plasma membrane to the cytoplasm and nucleus in gastric cancer, which was found to be significantly associated with worse clinical prognosis." (PMID 29451900, 2018). "ARID1A mutations are frequently in various tumors including gastric cancer, colorectal cancer, breast cancer, lung cancer and gynaecological cancer." (PMID 29451900, 2018). "ARID1A is frequently mutated in ovarian clear cell carcinomas, hepatocellular carcinomas (HCCs), and gastric cancers; ARID2 in HCCs; PBRM1 in renal cell carcinomas; and SMARCA4 in small cell carcinomas of the ovary of hypercalcemic type (SCCOHT)." (PMID 26812616, 2016). "ARID1A is a chromatin remodeler that appears to act as a tumor suppressor, and decreased expression of ARID1A is associated with poor prognosis in gastric cancer and hepatocellular carcinoma." (PMID 27590521, 2016). "For example, ARID1A mutations were frequently identified in gastric cancers with microsatellite instability and Epstein-Barr virus infection." (PMID 26569409, 2015). "Reduced ARID1A expression was associated with lymph node metastasis, tumor infiltration, and poor prognosis in patients with gastric carcinoma." (PMID 25975202, 2015).
gastric cancer (continued). "Seventy-five percent (24/32) of gastric cancers with ARID1A mutations immunohistochemically exhibited a loss or substantially lower ARID1A protein expression compared to cancers with the wild-type gene (p < 0.001)." (PMID 24036443, 2013). "A Kaplan-Meier survival analysis showed a significant correlation between the loss of ARID1A expression and poorer clinical outcome of gastric cancer patients after radical operation." (PMID 22808142, 2012). "In conclusion, we have demonstrated the loss of ARID1A expression in gastric cancer and its correlation with a more malignant phenotype and poorer prognosis in a large number of clinical samples." (PMID 22808142, 2012). "Mismatch repair-deficient (dMMR) gastric carcinomas often harbor ARID1A alteration, but a sharply demarcated undifferentiated/rhabdoid component with selective ARID1A loss is uncommon and may create a diagnostic dilemma." (PMID 42094876, 2026). "Indeed, ARID1A-deficient gastric cancer cells have shown pronounced genomic instability and apoptotic cell death following ATR inhibition, both in vitro and in patient-derived organoid models." (PMID 40869030, 2025). "Among these, the AT-interacting domain-rich protein 1A (ARID1A), an accessory subunit, contains mutations in ∼50% of ovarian clear cell carcinoma cases, as well as in gastric cancer (∼20%), bladder cancer (∼20%), liver cancer (∼15%), colorectal cancer, and breast cancer." (PMID 40087883, 2025). "The group with SOX2 suppression had higher rates of mutations in many gastric cancer-associated genes such as epigenetic modifiers ARID1A, KMT2D, KMT2C, and KMT2B, as well as higher rates of mutations in genes encoding for receptor tyrosine kinases ERBB4 and FGFR1." (PMID 40149431, 2025). "Moreover, in early gastric cancer cases, ARID1A loss was frequently detected in EBV-associated gastric cancer cases." (PMID 38893181, 2024). "ARID1A mutations are emerging as a prognostic and predictive factor in gastric cancer." (PMID 38893181, 2024). "In gastric cancer, ARID1A deficiency was correlated with dMMR and increased expression of PD-L1." (PMID 38166741, 2024). "Combined with the evidence of the tumor suppressive effect of ARID1A in gastric cancer, the poor prognosis of high-risk patients may be related to the deletion of expression caused by ARID1A mutation." (PMID 37197421, 2023). "Furthermore, EZH2 inhibition has been shown to provide a specific vulnerability for ARID1A-mutated ovarian and gastric cancers, further supporting the interactions between writers and readers in cancer." (PMID 36653445, 2023). "CDH1 and ARID1A identified in LP were commonly mutated in gastric cancer." (PMID 36703611, 2023). "In addition, the loss of ARID1A caused worse differentiation and deeper tumor invasion in gastric cancer." (PMID 37366273, 2023). "It was also demonstrated that EZH2 inhibitors could reduce the viability of ARID1A-deficient cells in a dose-dependent manner in patients with gastric cancer." (PMID 37175555, 2023). "Loss of ARID1A resulted in higher T stage, worse differentiation, and E‐cadherin deficiency in this study, which are well‐known factors contributing to poor prognosis in gastric cancer." (PMID 37366273, 2023). "Given its association with genomic instability, we conducted this study to determine whether ARID1A mutation status had an impact on therapeutic responsiveness in gastric cancer (GC), especially combinatory chemo-immunotherapy." (PMID 36369379, 2023). "On the contrary, in gastric cancer, loss of ARID1A expression predicts poor overall survival (OS)." (PMID 37711591, 2023). "microRNA (miRNA) associated with AT‐rich interaction domain 1A (ARID1A) in gastric cancer." (PMID 38041544, 2023). "However, the mutation rate of ARID1A is 12- to 61-fold higher than the background mutation rate in MSI gastric cancers." (PMID 38275587, 2023).
gastric cancer (continued). "Loss of ARID1A, a tumor suppressor gene, has been shown to have significant prognostic value in several malignancies, gastric cancer, lung cancer, hepatocellular carcinoma, breast cancer, osteosarcoma, clear cell renal carcinoma, and small intestinal carcinoma." (PMID 36123603, 2022). "With 68% involving CG dinucleotides, C to T transitions are the most common mutation (51%) across all gastric cancers, while ARID1A mutations in GC usually contain indels relating to short C or G mononucleotide repeats, implying their occurrence by mismatch defect-induced microsatellite instability." (PMID 34671561, 2021). "In gastric cancer, ARID1A is frequently mutated in two molecular subtypes, EBVaGC and MSI." (PMID 34469459, 2021). "MiR-223 targets ARID1A, promoting cell proliferation and migration, suggesting that the NF-κB/miR-223-3p/ARID1A axis may promote H. pylori-induced chronic inflammation associated with gastric carcinoma." (PMID 34956210, 2021). "The data indicate that ARID1A expression may serve as a prognostic biomarker to identify high-risk gastric cancer patients, especially in early-stage undifferentiated cases." (PMID 31043675, 2019). "Taken together, our findings suggested NF-κB/miR-223-3p/ARID1A axis may link the process of H. pylori-induced chronic inflammation to gastric cancer, thereby providing a new insight into the mechanism underlying H. pylori-associated gastric diseases." (PMID 29317648, 2018). "In stomach cancer, ARID1A mutations result in lost expression and obtain a better prognosis." (PMID 26904685, 2016). "Several genome-wide sequencing studies have uncovered frequent ARID1A mutations in a multitude of human cancers including subtypes of ovarian, endometrial, uterine cancers, gastric carcinoma, esophageal adenocarcinoma, breast cancer and transitional cell carcinoma of the bladder." (PMID 25975202, 2015). "An association between PIK3CA and ARID1A mutations has also been reported in gastric cancer." (PMID 24036443, 2013). "Moreover, the mutation spectrum of ARID1A is distinct between the two genetic types of gastric cancer, with most indels in the MSI type and more single-neucliotide variations in the MSS type." (PMID 22808142, 2012). "Recently, exome sequencing study revealed that ARID1A is also frequently mutated in gastric cancer." (PMID 22808142, 2012). "Taken together, our observations that the loss of ARID1A expression in gastric cancer is associated with more malignant phenotypes and a worse prognosis imply that it may play a tumor suppressor role in gastric carcinogenesis." (PMID 22808142, 2012). "Moreover, relative to HER2‐positive gastric cancer, HER2‐negative gastric cancer cases with ARID1A mutation may be hot tumors that are responsive to immune checkpoint inhibitors." (PMID 37325934, 2023). "Additionally, increased sensitivity of ARID1A-deficient cancer cells to treatment with small molecule inhibitor of the PI3K/AKT pathway or selective sensitivity of EZH2 inhibitors against ARID1A-deficient gastric cancer could be demonstrated." (PMID 34359794, 2021). "Alterations in ARID1A may be diverse and have been observed in a variety of cancer types, including urothelial carcinoma, gastric cancer and lung cancer and the variants of ARID1A gene could also be detected through liquid biopsy even for cancers of unknown primary as well." (PMID 34715776, 2021).
gastric cancer (continued). "It has been shown that ARID1A was mutated and downregulated in GC and restoring ARID1A expression in gastric cancer cells significantly inhibited cell proliferation and colony formation." (PMID 31210753, 2019). "The chromatin remodeling gene, AT-rich interactive domain 1A gene (ARID1A), frequently mutates inactively in gastric cancer (GC)." (PMID 27354232, 2016). "In gastric cancer, it was shown that when ARID1A is lost an increase in PD-L1 protein expression is seen; this finding was attributed to an uptick in activity of the P13K-AKT signaling pathway which promotes growth and cell division." (PMID 40429787, 2025). "Mutations in the ARID1A gene, an integral component of the SWI/SNF complex, are prevalent, affecting prognosis and immune response in several malignancies, including gastric cancer (GC)." (PMID 40406134, 2025). "This bidirectional immunoregulatory signature establishes ARID1A as a key modulator of tumor-immune interactions in gastric cancer." (PMID 41215803, 2025). "While our study supports this triple therapy for ARID1A-hypermethylated gastric cancer, its clinical use requires careful toxicity management: Blood-related side effects from 5-aza-CdR can be reduced using lower doses (0.1 mg/kg)." (PMID 41215803, 2025). "This study aimed to systematically explore epigenetic regulation of ARID1A, specifically promoter hypermethylation, in gastric cancer (GC) and its functional/immunological consequences." (PMID 41215803, 2025). "It has been shown that when ARID1A expression is low in gastric cancer, the CD47 protein is elevated so that the immune response by M1 macrophages can be negated via increased T regulatory cells and M2 macrophages." (PMID 40429787, 2025). "Together, these results identify ARID1A promoter hypermethylation as a critical driver of gastric cancer progression and highlight the therapeutic potential of 5-aza-CdR in HGC-27 cells via promoting apoptosis and suppressing proliferation and invasion." (PMID 41215803, 2025). "It has been demonstrated that ARID1A alterations compromise the mismatch repair system; thus ARID1A defects are associated with MSI and high TMB, which can ultimately affect disease-free survival and overall survival of patients with advanced gastric cancer." (PMID 39028418, 2024). "Knockdown of ARID1A enhanced migration and invasion of gastric cancer cells, and exogenous overexpression of ARID1A inhibited cell migration." (PMID 39697230, 2024). "This suggests that low expression or deletion of ARID1A enhances migration and invasion of gastric cancer cells by down-regulating E-cadherin." (PMID 39697230, 2024). "Some clinical data suggest that alterations in ARID1A are found in 73% of EBV-positive gastric cancers and correlate with high PD-L1 expression." (PMID 39697230, 2024). "Our primary aim was to contribute theoretical support for future research on utilizing ARID1A as a biomarker to stratify individuals with gastric cancer and enable precision therapy." (PMID 38893181, 2024). "Mechanistically, previous studies proved that ARID1A expression loss activates the PI3K/Akt pathway to induce oncogenic effects in multiple malignancies, including gastric cancer, gynecological cancers and lung cancer." (PMID 36869329, 2023).